CCL5 (C-C motif chemokine ligand 5)
Diseases named in the same sentence as CCL5 in open-access papers (continued):
Sharing a sentence is not in itself a finding about the gene and the disease.
asthma (continued). "In previous studies, the −28C/G allele of the CCL5 promoter region was uniquely associated with nonallergic asthma in the Japanese population, and a cluster research found that the polymorphism in SRP9 (rs4653433) was related to nonallergic asthma." (PMID 29751569, 2018). "Compared to healthy control subjects, patients with asthma had significantly more percentages of eosinophils and neutrophils, IL-1RA, IL-1α, IL-1β, IL-2Rα, IL-5, IL-6, IL-7, IL-8, G-CSF, GROα (CXCL1), MIP-1β (CCL4), MIG (CXCL9), RANTES (CCL5) and TRAIL in their BAL fluids." (PMID 26011707, 2015). "Therefore, effector cells including T cells, NK cells, and DCs may be recruited via MC‐derived chemokines including CXCL10 and CCL5 during HRV infection; however, whether inflammatory cell recruitment would result in viral clearance or contribute to asthma pathology requires further investigation." (PMID 28008678, 2017). "Finally, while most evidence reflects an important role of CCL5 and the eotaxins in asthma, some studies reported that there was no increase in CCL5 or eotaxin expression in BAL, airway epithelium brushings, or bronchial biopsies between asthmatics and healthy controls." (PMID 28848734, 2017). "Consistent with unchanged T cell Ccl4 levels following experimental asthma induction, Mdk levels were similar in OVA- and HDM-treated Nf1OPG mice relative to controls, and Mdk does not induce Ccl5 production in microglia." (PMID 34880260, 2021). "We have also shown that histamine enhances IL-1β-induced granulocyte-macrophage colony stimulating factor (GM-CSF) release but strongly inhibits CCL5 (RANTES) release by ASM cells from people with and without asthma." (PMID 24648846, 2014). "Few sputum cytokine concentrations changed in response to dexamethasone IL-17 and IFNα increased in smokers, CCL4 increased in never smokers and CCL5 and CXCL10 reduced in ex-smokers with asthma." (PMID 23951170, 2013). "For other asthma-relevant genes such as TNF, IL-4, IL-10, CCL12 (MCP-5), CCL5 (RANTES), and CCR3, there were no significant IL-13-inducible or statin effects on gene expression." (PMID 22583375, 2012). "Another group showed that severe asthma was neither TH1 or TH2, but severe asthma was characterized by elevations in BAL CXCL1 (growth-related oncogene, GRO), RANTES (regulated on activation, normal T cell-expressed and -secreted, CCL5), IL-12, interferon (IFN)-γ and IL-10." (PMID 39596984, 2024). "Since T cell Ccl4 levels were not reduced by experimental asthma induction, we hypothesized that OVA- and HDM-treated Nf1OPG mouse T cells might produce an inhibitor of microglia Ccl5 production." (PMID 34880260, 2021). "Besides inhibition of eotaxin-1 and MCP expression by simvastatin, neither IL-13 nor simvastatin treatment changed the expression of other asthma-relevant Th2-type cytokines such as IL-4, CCL5 (RANTES), CCR3, or IL-5Ra." (PMID 22583375, 2012).
Obesity (98 papers, 2009 to 2026). Accumulation of substantial excess body fat. "The identification of SPP1, ITK, and CCL5 as immune hub genes in the adipose tissue of postmenopausal obese women provides new insights into the immune dysregulation associated with obesity." (PMID 40725440, 2025). "In summary, this study employed bioinformatics analysis of microarray and scRNA-seq datasets to identify three immune hub genes—SPP1, ITK, and CCL5—associated with obesity." (PMID 40725440, 2025). "Physical activity was associated with reduced expression of CCL5 in adipose tissue of patients with obesity." (PMID 39275140, 2024). "CCL5 is thought to be associated with IR in relation to age, HbA1c, obesity, and other factors, although the number of studies is limited." (PMID 39063997, 2024). "We found increased levels of CCL5 in patients with obesity and obesity-associated T2D, with also higher levels of IL-6 and the ratio IL-18/IL-18BP." (PMID 38315242, 2024). "For instance, C-C motif chemokine ligand 2 (CCL2) and C-C motif chemokine ligand 5 (CCL5) are closely associated with obesity-induced cardiovascular disease and insulin resistance." (PMID 39334887, 2024). "The expression levels of CCR5 and CCL5 were found to be significantly elevated in adipose tissue during inflammation and insulin resistance associated with obesity." (PMID 39334887, 2024). "The review examines the association of CCL5 with periodontitis risk factors, including aging, cigarette smoking, diabetes, and obesity." (PMID 38139161, 2023). "The results of studies on the association of CCL5 expression with periodontal disease depending on patient risk factors such as age, obesity, smoking, and diabetes are inconclusive." (PMID 38139161, 2023). "CCL5 directly affects insulin signalling, and aggravates inflammatory responses in adipocytes, causing insulin resistance and obesity." (PMID 37778719, 2023). "The mRNA levels of Cd8, iNOS, TNF-α, and IL-1β were increased in obese CCL5 KO mice than in obese WT mice, indicating that CCL5 deficiency also exacerbates liver inflammation in obesity." (PMID 36713454, 2022). "CCL5 deficiency enhanced glucose tolerance in lean mice but exacerbated insulin resistance and adipose inflammation in obesity." (PMID 36713454, 2022). "The C-C chemokine motif ligand 5 (CCL5) and its receptors have recently been thought to be substantially involved in the development of obesity-associated adipose tissue inflammation and insulin resistance." (PMID 36430701, 2022). "Consistent with ITT results, the pAkt/Akt ratio was decreased in eWAT, liver, and muscle of CCL5 KO mice, indicating that CCL5 deficiency significantly attenuated insulin signal transduction in classic insulin target organs in obesity." (PMID 36713454, 2022). "We further analyzed in eWAT the expression of Arg1, a hallmark of alternatively activated macrophages and Ccl5 given its role in local inflammation of visceral WAT in obesity." (PMID 33924880, 2021). "It has been recently reported that CCL2 and CCL5 are linked to the obesity-associated infiltration by monocytes/macrophages of adipose tissues." (PMID 31817755, 2019). "The chemokine CCL5, also known as RANTES for Regulated on Activation, Normal T Cell Expressed and Secreted, has already been linked to obesity-associated inflammation in periphery." (PMID 28855891, 2017). "MCP-1 and CCL5/RANTES are risk markers closely associated to obesity related risk factors, i.e. dyslipidaemia and insulin resistance." (PMID 22011432, 2011). "Notably, CCL5 deficiency has been shown to protect against adipose tissue inflammation in obesity, yet it has also been shown to exacerbate kidney injury in hypertensive models." (PMID 40563378, 2025). "Moreover, a previous study reported elevated serum levels of CCL5 in patients with type 2 diabetes, highlighting its potential association with IR in individuals with obesity." (PMID 40423250, 2025).
Obesity (continued). "Interestingly, CCL5, which is associated with macrophage recruitment and M1 polarization during obesity-induced inflammation, exhibited a different pattern." (PMID 40395977, 2025). "CCL5 was previously found to be secreted by macrophages in obesity-associated adipose tissue." (PMID 39275140, 2024). "Chemokines CCL2 and CCL5 have been associated with elevated levels in adipose tissue in obesity." (PMID 39334887, 2024). "Furthermore, CCL5 influenced the composition of immune cell populations within the adipose tissue, potentially contributing to a decreased risk of developing obesity-associated insulin resistance." (PMID 39334887, 2024). "We next sought to examine the role of CCL5 in obesity-associated MDSC accumulation in eWAT." (PMID 36430701, 2022). "However, the mechanisms underlying immunocytes contributed to the obesity-induced nonalcoholic steatohepatitis in CCL5 deficient mice still need to be clarified." (PMID 36713454, 2022). "Together, these data indicate that CCL5 deficiency aggravates obesity-induced liver injury." (PMID 36713454, 2022). "Indeed, obesity is associated with an increase in CCL5 secretion and gene expression in AT in obese human and mice." (PMID 28855891, 2017). "Whether CCL5 is a cause or a consequence of obesity, or if it could effectively disrupt the proper function of the neuropeptidergic circuits of the hypothalamus, which regulate energy balance and promote the establishment of obesity, is nevertheless still matter of investigation." (PMID 28855891, 2017). "Consistently, decreased methylation in the promoter region of the CCL5 gene was observed in peripheral blood mononuclear cells (PBMCs) of preadolescents with obesity, aligning with elevated CCL5 expression compared to healthy controls." (PMID 40423250, 2025). "CCL5 (alias regulated on activation normal T-cell expressed and secreted (RANTES)) associated with obesity is an important recruiter of monocytic myeloid-derived suppressor cells (MDSCs)." (PMID 40076892, 2025). "In HFD-induced obesity, the AT-derived expression of chemokine (C-C motif) ligand 5 (CCL5) enhances the local accumulation of pro-inflammatory M-MDSCs and subsequent inflammation via their cognate CCR5 receptors." (PMID 39967660, 2025). "Obesity, another risk factor for pancreatic cancer, can induce inflammation by promoting the release of IL-6, CCL2, and CCL5, and the infiltration of macrophages and immunosuppressive cells." (PMID 36899319, 2023). "Among the rNK cells, cluster C0 expressed mediators known to participate in inflammation during obesity (CCL5 and IL32)." (PMID 37063898, 2023). "In this study, we identified the major cellular source of CCL5 in obese mice and employed CCL5 knockout (KO) mice to determine the role of CCL5 in obesity-induced adipose inflammation and insulin resistance." (PMID 36713454, 2022). "The mRNA expression level of CCL5 was induced by obesity more markedly in the stromal vascular fraction (SVF) than in adipocytes." (PMID 36713454, 2022). "The present results further provide in vivo evidence supporting the importance of tissue-derived CCL5 in the etiology of obesity-induced adipose tissue inflammation and insulin resistance." (PMID 36430701, 2022). "Several groups have attempted to identify the role of CCR5, a major receptor of CCL5 in adipose tissue, in obesity-induced insulin resistance." (PMID 36713454, 2022). "Whilst being associated with hepatic steatosis, the regulation and role of CCL5 in obesity requires further elucidation." (PMID 36430499, 2022). "We identified that CD8+ T cells are the major cellular sources responsible for upregulation of CCL5 by obesity in eWAT." (PMID 36713454, 2022). "As a consequence, the reduction in adiponectin levels during obesity results in increased RANTES/CCL5 levels, which should induce an increase in insulin secretion." (PMID 35628332, 2022).
Obesity (continued). "Our study used loss- and gain-of-function approaches to reveal the role of adipose tissue CCL5 in M-MDSCs subpopulation and trans-differentiation of tissue macrophages in obesity-induced adipose tissue inflammation." (PMID 36430701, 2022). "Elevated CCL-5 levels (RANTES) have been described as a marker of progression towards type 2 DM in patients with obesity and carbohydrate intolerance when compared to healthy subjects." (PMID 35955802, 2022). "First, the expression of CCL5 is increased in eWAT of HFD-induced obesity, particularly in CD8+ T cells within eWAT." (PMID 36713454, 2022). "The observed reduction of CCL5 concentrations were presumably due to a general improvement of the obesity-related, low-grade inflammation state during and as a consequence of considerable weight loss." (PMID 36430499, 2022). "MCP1 and CCL5 are key chemokines that are upregulated in obesity and function to recruit monocytes to inflammatory sites." (PMID 35422759, 2022). "To investigate the regulation of CCL5 expression by obesity in metabolic tissues, we analyzed mRNA levels of CCL5 and its receptors in adipose tissues, liver, and skeletal muscle from ND and HFD-fed mice." (PMID 36713454, 2022). "CCL5, also known to be regulated on activation, normal T-cell expressed, and secreted (RANTES), increases in the adipose tissue in murine and human obesity, and adipose CCL5 expression was comparatively higher in obese individuals than in lean individuals." (PMID 34360840, 2021). "Growing evidence has revealed that obesity is associated with immune response involving chemokines secreted by immune cells, such as CCL2, and CCL5." (PMID 34948325, 2021). "For instance, the expression of CCL5 and CCL20 has been associated with fatty liver disease, while CXCL5 is an adipose tissue derived factor associated with obesity." (PMID 32764789, 2020). "Obesity that is characterized by chronic low-grade systemic inflammation is associated with an elevated level of CCL2 and CCL5, which are the major chemokines involved in macrophage infiltration and the alteration of decoy receptor expression." (PMID 31817755, 2019). "Earlier research concluded that obesity is associated with an increased accumulation of T cells and macrophages in adipose tissue, and CCL5 is an adipokine that is upregulated in adipose tissue through obesity in humans." (PMID 26276522, 2015). "Our data indicate that besides CCL2 and CCL5, numerous other chemokines such as CCL19 are expressed by adipocytes under obesity-associated chronic inflammation." (PMID 23824685, 2013). "B and T lymphocytes are recruited during early obesity-induced inflammation by preadipocytes or chemotactic adipokines like CCL5, CXCL5, CXCL12, or CCL20." (PMID 24106481, 2013). "Studies have shown that obesity-induced adipose tissue enhances CCL5/CCR5 signal transduction." (PMID 40725440, 2025). "Interestingly, a cross-sectional study involving children with obesity revealed a significant increase in CCL5 expression compared to eutrophic children." (PMID 40423250, 2025). "However, a recent study reported that ASC-mediated CCL5 plays a crucial role in T-cell accumulation within adipose tissue, antagonizing obesity-induced inflammation." (PMID 40395977, 2025). "CCL5 probably also plays an important role in obesity as shown in animal models." (PMID 39457105, 2024). "Moreover, the mRNA expression of Ccl5 displayed a significant increase in HF-fed young mice, aged mice, and particularly in the group with the combination of aging and obesity, with an apparent age and diet effect noted through the two-way ANOVA analysis." (PMID 39009694, 2024). "Moreover, a solid combined impact of aging and obesity for Tnf and Ccl5 mRNA expression was observed with a trend for Mcp1." (PMID 39009694, 2024).
Obesity (continued). "Taken together, these data clearly suggest that Ac-iNKT1 cells could selectively remove hypertrophic and pro-inflammatory adipocytes and would recruit macrophages via CCL5 to clean up dead adipocytes in obesity." (PMID 38129377, 2023). "Since the previous reports demonstrated the alteration of IL1A, CCL5, and OX40 in the Lkb1-deficient DC and expression of those genes are also well known to regulate adipose tissue inflammation in obesity, we examined the expression of those essential genes on ATM and ATDC." (PMID 36781473, 2023). "In support of this, CCL5/RANTES has also been found to be overexpressed in obese adipose tissue, and implicated in macrophage accumulation and survival, inflammation and insulin resistance in the visceral adipose tissue during obesity." (PMID 37509065, 2023). "To identify the dominant cellular sources responsible for the upregulation of CCL5 in eWAT by obesity, we detected the expression of CCL5 in CD4+ T cells, CD8+ T cells, macrophages, and adipose tissue stem cells (ASCs) in eWAT from lean and obese mice by flow cytometry." (PMID 36713454, 2022). "Obesity-induced increases in adipose tissue CCL5-mediated signaling in adipose tissue is crucial for the recruitment of circulating M-MDSCs and trans-differentiation to tissue pro-inflammatory M-MDSCs and macrophages, resulting in adipose tissue inflammation and insulin resistance." (PMID 36430701, 2022). "To determine whether CCL5 is required for obesity-induced adipose tissue inflammation and insulin resistance, we first examined the metabolic phenotype of global CCL5 knockout (CCL5KO) mice." (PMID 36430701, 2022). "Therefore, the role of CCL5 in obesity-induced adipose inflammation and insulin resistance is obscure." (PMID 36713454, 2022). "However, the link between adipose tissue-derived CCL5 in the circulation and tissue M-MDSCs in the development of obesity remains elusive." (PMID 36430701, 2022). "We, therefore, examined the obesity-induced hepatic steatosis in WT and CCL5 KO mice." (PMID 36713454, 2022). "To investigate whether CCL5 is specifically increased in CD8+ T cells in adipose tissues during obesity, we examined the percentage of CCL5 positive CD8+ T cells in peripheral blood, mesenteric lymph nodes, and spleen of lean and obese mice." (PMID 36713454, 2022). "RANTES/CCL5 is an interesting chemokine whose levels are increased during obesity is." (PMID 35628332, 2022). "As CCL5 could promote macrophage recruitment, CCL5 may be an essential chemokine secreted by CD8+ T cells to enhance the recruitment of macrophages during the development of obesity-induced adipose tissue inflammation." (PMID 36713454, 2022). "To investigate whether CCL5 participates in obesity-induced adipose inflammation, we detected immunocyte accumulation in the eWAT of obese WT and CCL5 KO mice." (PMID 36713454, 2022). "However, the pathological and physiological roles of CCL5-mediated signaling in obesity-related dysregulation of energy metabolism remain mostly unclear." (PMID 34948325, 2021). "However, ST2 deficiency did cause significant reductions in serum IL-1β, TNFα, and CCL5 in the HFD-fed mice, suggesting that IL-33 contributes to aspects of the systemic inflammation of obesity." (PMID 32326950, 2020). "We wanted to know if adipose CCL5 expression was elevated in obesity and whether these changes correlated with those of IRF5 mRNA expression in the adipose tissue." (PMID 31718015, 2019). "Interestingly, in this current study the mice with obesity and cholangitis were found to have predominately CCL5− neutrophils in the liver as well as higher serum levels of CCL3 and CCL5." (PMID 29449577, 2018). "Notably, increased adipose tissue levels of multiple β-chemokines (CCL2, CCL3, CCL5, CCL7, CCL8, CCL11) and chemokine receptors (CCR1, CCR2, CCR3, CCR5) have been linked with obesity and associated metabolic inflammation." (PMID 28396851, 2017).